CAV1 (caveolin 1)
Diseases named in the same sentence as CAV1 in open-access papers (continued):
Sharing a sentence is not in itself a finding about the gene and the disease.
tumor (continued). "Thus, the impairment of tumor-induced angiogenesis in Cav-1−/− mice was attributed to the absence of Cav-1 and not of Cav-2." (PMID 29250058, 2017). "We showed high protein expression of caveolin-1 and collagen VI in the I/H-related subtype, but as the TCGA group reported, it is possible that these proteins were not specific to tumor but were produced by the microenvironment and/or cancer-activated fibroblasts." (PMID 29050296, 2017). "It is assumed that regulated Cav1 expression in the cancer cells is a prerequisite for their hyperproliferative stage and that Cav1 might regulate tumor-promoting epithelial-mesenchymal transition (EMT) of the transformed epithelial cells, tumor angiogenesis and metastasis." (PMID 28112237, 2017). "Whether in vitro or in animal or in cancer patients, CAV1 is a tumor promoter gene or tumor suppressor gene that has not been consistent." (PMID 29190968, 2017). "Therefore, Cav-1 represents one critical modulator of the RAF-ERK negative feedback loop, adding a new mechanism by which Cav-1 functions as a regulator of tumor growth." (PMID 29141593, 2017). "EGF-induced tumor cell proliferation and migration is suppressed when Cav-1 binds to the EGFR, suggesting that Cav-1 may play a role in maintaining the EGFR in an inactive state, with dissociation from Cav-1 promoting EGFR activation." (PMID 29141593, 2017). "Therefore, phosphorylation of Y14 in the CAV1 protein can be therapeutically targeted to selectively diminish metastasis without inhibiting the tumor suppressor function of CAV1." (PMID 27259249, 2016). "Importantly patients with high Cav-1 expression in the tumor stroma had an excellent outcome also in the absence of active treatment." (PMID 27764093, 2016). "As a result, they found that expression of CAV1 in TSCC had a higher score in exosomes than in the tumor cells and a negative impact on recurrence (p = 0.01) and survival (p = 0.003), which suggested that accumulation of CAV1 in exosomes had a negative prognostic value in TSCC." (PMID 27756426, 2016). "LSS exposure was found to induce mechanosensitive Cav-1 activation and PI3K/Akt/mTOR signaling cascade, which increase the MT1-MMP expression and translocation, cytoskeleton reorganization, invadopodia formation and ECM degradation, leading to promotion of tumor cell motility and metastasis." (PMID 26919102, 2016). "However, it has been proposed that glutamine availability inversely correlates with CAV1 expression in tumour stromal compartment, and that fibroblasts lacking CAV1 secrete more glutamine." (PMID 27852311, 2016). "LSS exposure was found to induce Cav-1 activation and PI3K/Akt/mTOR signaling cascade and to increase MT1-MMP expression and trafficking, cytoskeleton reorganization, invadopodia formation and ECM degradation, leading to promotion of tumor cell motility and metastasis." (PMID 26919102, 2016). "However, the role of Cav-1 in the molecular cross-talk between tumor and stroma is not yet well characterized." (PMID 26828520, 2016). "Although there was no observed difference in primary tumor growth when Cav1 was absent in the tumoral stroma specifically, a decrease in primary tumor growth was observed when the whole mammary gland was deficient for Cav1 in mammary gland allografts and xenografts." (PMID 26179155, 2015). "Notably, a significant gene upregulation of hypoxic target genes (65 transcripts), glycolysis/pyruvate metabolism (15 transcripts), and autophagy (22 transcripts) were involved in the Cav-1-negative (−) tumor stroma." (PMID 26431273, 2015). "In addition, CAV1 and β-catenin were mostly delocalized from the membrane in NRAS-ΔPTEN tumours." (PMID 26307673, 2015). "Caveolin-1 (CAV1) may be upregulated by hypoxia and acts in a tumor-dependent manner." (PMID 25633184, 2015).
tumor (continued). "However, caveolin-1 plays complex roles in cancer, with no existing models to explain its apparent contradictory tumor promoter and suppressor roles." (PMID 25924234, 2015). "However, although no expression of CAV1 was detected in tumor samples no methylation was observed in its promoter, suggesting that promoter hypermethylation is a secondary event to gene silencing which would be induced by other mechanisms." (PMID 25313138, 2014). "Cav-1 expression in human cancer cells is not considered to conform with that in the tumor stroma." (PMID 25202343, 2014). "We also found positive staining of N-cadherin in tumor mesenchymal tissues from both Huh7 Cav-1 group and Huh7 Vector group (as labelled by black arrows), whereas no positive staining of N-cadherin was detected in tumor parenchymal tissues from Huh7 Vector group." (PMID 24454730, 2014). "However, Cav-1 has been reported to influence both positively and negatively various aspects of tumor progression and to act as tumor suppressor or poor prognostic factor in many human cancers." (PMID 24738074, 2014). "It has been demonstrated that caveolin-1 (Cav-1), produced by CAFs, alters the alignment of ECM proteins and promotes stiffness of the tumour stroma, thereby resulting in force-dependent Rho GTPase activation and the stimulation of tumour invasion and metastasis." (PMID 24216702, 2013). "Moreover, both tumor cells and CAFs Cav-1 protein expression status were not correlated to the typical clinicopathological parameters, such as T stage, TNM stage and Lauren classification." (PMID 23527097, 2013). "In the two discordant cases Cav-1 was expressed in the primary tumour but not in the secondary." (PMID 24119769, 2013). "We previously hypothesized that the high levels of caveolin-1 expression in bladder, colon, esophageal and prostate cancers promote cell surface proteolytic events that lead to extracellular matrix (ECM) degradation and tumor invasion." (PMID 22093547, 2011). "The cell nuclei were CAV1 negative in all patients' tumor specimens." (PMID 22152020, 2011). "Whether there is a universal link between Rho, caveolin-1, cathepsin B, and acidification of the tumor microenvironment has not yet been evaluated." (PMID 22093547, 2011). "In conclusion, stepwise increase in Cav-1 expression in neoplastic stage with respect to pre-neoplastic stage during hepatocellular carcinogenesis and its ability to stimulate HCC cell motility and invasiveness indicate that this protein plays a crucial role in tumor progression." (PMID 19239691, 2009). "The carcinoma tumor sections were characterized by non-overlapping expression of Cav-1 and SMA." (PMID 18811984, 2008). "Furthermore, HT29(US) cells, which were obtained from secondary metastasis after injection into nude mice of primary tumour-derived HT29 cells, showed increased endogenous caveolin-1 when compared to the parental HT29 cells (Bender and Quest, unpublished data)." (PMID 18400052, 2008). "However, in this case it was found that cyclin D1 was up-regulated in the mammary lesions of the caveolin-1 null mice as compared to the normal tumour prone mice, but no change in the activation state of the p42/44 MAPK cascade was observed." (PMID 18949068, 2007). "The fact that caveolin-1 is capable of suppressing the activity of many components of growth factor signalling pathways (e.g., the EGFR and components of the p42/44 MAPK pathway), makes it an attractive candidate tumour suppressor gene, and several lines of evidence support this proposal." (PMID 18949068, 2007). "However, in 30% of cases tumour formation was not reduced, and in these cases it was found that tumour formation resulted in the selection of cells that did not contain caveolin-1." (PMID 18949068, 2007).
tumor (continued). "Our findings in this study suggest that the Cav-1/YAP axis may function as a key regulator of cell movement in the mechanical context of ECM fiber orientation, and provide a novel target for the prevention and treatment of cancer cell migration induced by collagen linearization in tumor tissue." (PMID 39318372, 2024). "Similarly, the expression of genes for cell differentiation (CAV1 for caveolin-1) and cell proliferation (MKI67 for marker of proliferation Ki-67 and PCNA for proliferating cell nuclear antigen) were down- and upregulated, respectively, in tumor samples (adjusted p value < 0.01)." (PMID 39062740, 2024). "At this time, it is not known whether the changes in stromal CAV1 are actively orchestrated by the tumor to reprogram the microenvironment or whether they represent adaptive changes of the stromal cells to the adjacent tumor." (PMID 35158857, 2022). "Moreover, tumor grading was available only for a few samples included in the study, so we could not assess the relationship between grading and Cav-1 expression." (PMID 34590611, 2021). "Indeed, higher levels of Cav-1 seemed to be detected in metastases rather than in primary tumor histological samples, thus leading to the assumption that Cav-1 expression might change based on tumor growth pattern." (PMID 34590611, 2021). "Hence, based on the overlapped upstream miRNAs and correlation analysis, we confirmed that the three key miRNAs (hsa-miR-124-3p, hsa-miR-26b-5p, and hsa-miR-192-5p) could regulate the four hub genes (CAV1, COL6A2, CSPG4, and PCOLCE) in GEM-resistance and tumor immune microenvironment." (PMID 35127724, 2021). "Additionally, in tumor cells, oxidative stress induces the activation of pro-autophagy factors, for instance, BNIP3L, LC3, BNIP3, ATG16L, HIF-1α and nuclear factor kappa B (NF-κB) to promote caveolin-1 (Cav-1) degradation, ultimately resulting in autophagy activation." (PMID 33525678, 2021). "However, the reduced expression level of CAV1 in EOC cells compared to noncancerous tissues may point to a role for CAV1 as a tumor suppressor gene." (PMID 32401768, 2020). "Furthermore, these analyses indicated that survival of patients with tumours expressing high APQ1 levels was shorter when compared to patients with low AQP1 expression and that the difference in survival was more significant in the case of joint high expression of AQP1 and CAV1." (PMID 32065471, 2020). "Similarly Cav-1 expression in the surrounding non-malignant stroma was correlated to Cav-1 immunoreactivity in the tumor stroma and to other tumor characteristics, but the correlations were rather weak and Cav-1 immunoreactivity in non-malignant stroma was not related to outcome." (PMID 27764093, 2016). "Hence, although not yet proven, CAV1 could play a role in c-MYC-driven glutamine metabolism in tumours." (PMID 27852311, 2016). "Importantly, however, CAV1 Y14 phosphorylation is not required for CAV1 tumor suppressor activity." (PMID 27259249, 2016). "Although this proteasome-like arrangement is conserved in mammalian cells, the data presented here suggest that the ClpP and ClpX subunits may not have completely overlapping function(s) in tumor mitochondria, especially with respect to Akt activation and Cav1-dependent tumor cell motility." (PMID 27389535, 2016). "Part of this variability could stem from Cav1 expression in stromal rather than tumor cells." (PMID 26179155, 2015).
tumor (continued). "Since caveolin-1 was found to translocate to the plasma membrane in the presence of BRCA1/BRCA1a proteins, we can speculate that this may provide an important mechanism for regulating the tumor suppression function in sporadic ovarian cancers where somatic mutations in BRCA1 are rarely found." (PMID 25594072, 2014). "Recently, several authors have focused their attention on Cav1 expression in the tumour stromal cells (stromal Cav1) rather than Cav1 cellular expression, as evidence suggests that there may be an important role for stromal Cav1 in promoting tumour progression and metastasis." (PMID 23521716, 2013). "It is noteworthy that the expression of Cav-1 in CAFs rather than tumor cells particularly applicable in predicting early recurrence and poor survival prospects of GC patients, suggesting Cav-1 in CAFs may be a candidate therapeutic target and a useful prognostic marker of GC patients." (PMID 23527097, 2013). "However, little evidence supported ST7 and CAV1 to be tumor suppressor genes in primary GC." (PMID 20626849, 2010). "Patients who had tumours that were positive for both caveolin-1 and pAKT had significantly worse prognosis than patients who had tumours that expressed neither biomarker or either caveolin-1 or pAKT alone, with a mean disease-free survival of 2.95 vs 6.14 years (P<0.0001)." (PMID 18283322, 2008). "Given the role of CD36 in enhancing ferroptosis through the transcriptional upregulation of CAV1 in TNBC, we further investigated the potential of ferroptosis activators to effectively inhibit TNBC tumor metastasis in the absence of CD36." (PMID 41267927, 2025). "CAV1 and MMP14 protein expression investigated by IHC increased gradually from nonbudding tumors to the bulk of budding tumors and tumor buds." (PMID 40082664, 2025). "It should also be mentioned that the cut-offs for CAV1-high and CAV1-low classifications of TNBC are relative to a population and not based on absolute cut-offs for each tumor." (PMID 38959243, 2024). "The study proposes a Cav1-mediated transcellular route, not the conventional EPR effect, for NP penetration into tumor vasculature." (PMID 39193389, 2024). "We show a negative correlation between CAV1 tumoral protein levels – a major protein of cholesterol-rich membrane domains – and Trastuzumab-drug conjugate TDM1 tumor uptake." (PMID 35534471, 2022). "PC3 PCa cells for example were shown to harbor high levels of non-caveolar CAV1 while lacking PTRF, and introducing PTRF in turn inhibited anchorage-independent growth, reduced in vivo tumor growth and metastasis." (PMID 35155239, 2022). "Caveolin-1 depletion did not affect the tumor growth of AGS cells, whereas it completely reversed the FTO-inhibited tumor growth and reduced the tumor weight." (PMID 35064107, 2022). "IHC results showed that the CAV1, AKR1C3, and TRIB3 protein expression levels were significantly higher in HNSCC tumor tissues (P < 0.05), but the difference in AURKA was not significant (P = 0.144)." (PMID 34539737, 2021). "The result of q-rtPCR showed that the mRNA expression levels of PTGS2, RRM2, AURKA, CAV1, MAP3K5, STEAPS are higher in tumor samples and lower in normal tissue samples and the others had the reverse tendency." (PMID 33819918, 2021). "Therefore, different subtypes might not influence the prediction of tumor Cav-1 expression on PFS." (PMID 30348118, 2018). "CAV1 is localized to 7q31.2, closed to D7S522 locus which is a fragile site that is frequently absent in cancer and is thought to be a suspected tumor suppressor locus." (PMID 29190968, 2017). "So, in our opinion this cell line is not representative of highly expressed CAV1 and therefore our panel of ARMS cells reflects better the role of CAV1 as a putative tumor suppressor in ARMS." (PMID 25313138, 2014). "Of IBC tumor cells that express cathepsin B (score of ++ or +++), 70% also expressed caveolin-1 (score of ++ or +++), whereas only 19% of non-IBC tumor cells showed this co-expression (P = 0.001)." (PMID 22093547, 2011).
tumor (continued). "However, the increased trastuzumab tumor accumulation (and improved tumor killing) was not due to increased HER2 caveolin-1-mediated endocytosis." (PMID 34358100, 2021). "However, the mechanism responsible for CAV1 absence and its putative role in ARMS as a tumor suppressor has not been investigated yet." (PMID 25313138, 2014). "We were able to confirm these results as CAV1 expression was detected in the tumor cell cytoplasm of 242 (83.7%) and the cell membrane of 232 (80.3%) patients with clear cell RCC, the cell nuclei were negative in all patients' tumor specimens." (PMID 22152020, 2011). "Interestingly, xenograft tumor lysates from the HC-D group showed higher expression of both IQGAP1 (2.85 ± 0.50, p = 0.003) and caveolin-1 (3.0 ± 0.7, p = 0.011), although cholesterol treatment of PC-3 cells in vitro increased expression of IQGAP1 but not caveolin-1." (PMID 25924234, 2015).